OSGIN1 (oxidative stress induced growth inhibitor 1)
Diseases named in the same sentence as OSGIN1 in open-access papers:
OSGIN1 is named in the same sentence as 23 diseases in open-access papers, as found by Europe PMC text mining. Sharing a sentence is not in itself a finding about the gene and the disease. The quoted sentences say what the papers report.
breast carcinoma (10 papers, 2011 to 2025). "Osgin1 has also been implicated in PI3K/Akt/Nrf2 pathways for responding to oxidative stress in breast cancer tumor reduction." (PMID 40149945, 2025). "Osgin1 also appears to be a part of wider physiological disruptions caused by breast cancer." (PMID 40149945, 2025). "The mechanistic pathway of Osgin1 in breast cancer was further explored with chorionic gonadotropin (CG)-mediated reduction in mammary carcinogenesis." (PMID 40149945, 2025). "While some Osgin1 expression was observed in the cells transfected with human breast cancer cell lines, these cells exhibited much lower expression compared with healthy tissue." (PMID 40149945, 2025). "Downregulation of PI3K/Akt/Nrf2 pathways all downregulated Osgin1 expression and its induction of apoptotic cell markers, overall supporting the potential use of DHA in inducing apoptosis in breast cancer through induction of Osgin1 in these pathways." (PMID 40149945, 2025). "It is also known that docosahexaenoic acid (DHA) activates NRF2 through ROS production and induces OSGIN1 expression in human breast cancer cell lines (MCF-7)." (PMID 38612696, 2024). "Docosahexaenoic acid-induced cell death in Breast cancer cells by upregulating OSGIN1 expression via PI3K/Akt/Nrf2 signaling pathway." (PMID 35615145, 2022). "In addition to breast cancer, the expression of Osgin1 and its mechanism and hepatocellular cancers have been studied in several papers." (PMID 40149945, 2025). "In addition, transfection of the overexpressed Osgin1 homolog protein in rat liver cells induced apoptosis, suggesting a possible link from CG treatment to mammary carcinoma destruction via upregulation of Osgin1." (PMID 40149945, 2025). "Finally, increased expression was examined through transfection of Osgin1 cDNA into MCF-7 breast cancer cells, with reduced tumor proliferation being measured in both in vitro and in vivo lactating rat models." (PMID 40149945, 2025). "In addition, DHA has been reported to trigger ROS generation and finally induce oxidative stress-induced growth inhibitor 1 (OSGIN1) expression in breast cancer cells." (PMID 31178955, 2019). "Separate DHA treatment and overexpression of Osgin1 in MCF-7 cells resulted in similar upregulation of p-AMPKαT172, supporting another possible pathway for Osgin1’s impact within breast cancer tissue." (PMID 40149945, 2025). "In addition, OSGIN1 also regulates the autophagy process by enhancing autophagosome formation in ROS-dependent pathways, which are associated with the activation of the AMPK/mTOR signaling pathway after docosahexaenoic acid (DHA) treatment in breast cancer cells." (PMID 35625730, 2022). "In addition, DHA was also reported as inducing the expression and nuclear translocation of the oxidative stress sensitive transcription factor, NFE2L2/Nrf2, and to increase the expression of oxidative stress-induced growth inhibitor 1 (OSGIN1) in MCF-7 and Hs578T breast cancer cells." (PMID 35805595, 2022).
hepatocellular carcinoma (5 papers, 2015 to 2025). A malignant tumor that arises from hepatocytes. "As a tumor suppressor, downregulation of OSGIN1 was also found to be closely associated with progression of other malignancies such as hepatocellular carcinoma and kidney cancer." (PMID 25860939, 2015). "OSGIN1 is a tumor suppressor that induces apoptosis through translocation to mitochondria and increasing the release of cytochrome c; meanwhile, OSGIN1 is associated with hepatocellular carcinoma (HCC) progression and patient survival." (PMID 35625730, 2022). "The role of 5′ UTRs has also been shown to be essential in the downregulation of Osgin1 in hepatocellular cancers." (PMID 40149945, 2025). "Through immunohistochemistry, OSGIN-1 was found to be at reduced or even undetectable levels in 74 of 92 hepatocellular carcinoma samples included in the study, matching the prior work with mammary gland carcinoma." (PMID 40149945, 2025). "OSGIN1 was regulated by long non-coding RNA (lnRNA) UCA1 to mitigate autophagy flux-mediated apoptosis through the mTOR pathway in human hepatocellular carcinoma cells (HepG2) under arsenic toxicity." (PMID 35625730, 2022). "Oxidative stress induced growth inhibitor 1(OSGIN1) is a tumor suppressor gene linked to cellular stress and apoptosis, variants of which have been implicated in cancer development, specifically in hepatocellular carcinoma." (PMID 32751422, 2020). "Therefore, the role of Osgin1 in hepatocellular carcinomas may stem from both downregulation and increased expression of less effective mutated transcripts." (PMID 40149945, 2025). "Similar to their findings with mammary gland and hepatocellular carcinomas, Western blot and immunohistochemical studies showed low expression or even undetectable levels of Osgin1 in kidney tumors in comparison with surrounding non-cancerous tissue." (PMID 40149945, 2025).
pancreatitis (3 papers, 2022 to 2025). Inflammation of the pancreas. "Consistent with the findings with these studies, overexpression of OSGIN1 stimulated autophagic flux in pancreatitis tissues and cell lines, which was similar to the effect of GW4064 treatment." (PMID 36405253, 2022). "It showed that autophagic vesicles were dramatically accumulated in pancreatitis tissues and were significantly reduced by OSGIN1-OE or GW4064 treatment." (PMID 36405253, 2022). "We further assessed the clinical significance of OSGIN1 in pancreatitis by IHC and found that OSGIN1 level in human pancreatitis tissues was significantly elevated compared to that in normal pancreatic tissues." (PMID 36405253, 2022). "In caerulein-induced mouse models of pancreatitis, OSGIN1 overexpression significantly reduced the accumulation of p62 and increased the ratio of LC3-II to LC3-I, which was consistent with the results in GW4064 treatment." (PMID 36405253, 2022). "Pancreatic knockdown of Osgin1 by AAV-pan abolished the therapeutic effects of FXR activation on pancreatitis, whereas pancreatic overexpression of Osgin1 effectively alleviated caerulein-induced pancreatitis." (PMID 36405253, 2022). "We find that OSGIN1 is elevated in human pancreatitis tissues and positively correlated with nuclear FXR expression." (PMID 36405253, 2022). "Activation of pancreatic acinar FXR restores efficient autophagy by promoting OSGIN1 expression to ameliorate pancreatitis." (PMID 36405253, 2022). "Furthermore, they found that suppression of FXR or inhibition of pancreatic Osgin1 led to more severe pancreatitis in murine models of CAE-induced AP." (PMID 40243995, 2025). "Meanwhile, we found that Osgin1 knockdown exacerbated pancreatitis." (PMID 36405253, 2022). "The FXR agonist GW4064 exhibited excellent therapeutic effects on pancreatitis; it could directly activate pancreatic acinar FXR to restore efficient autophagy mediated by enhanced Osgin1 expression, thus mitigate the severity of pancreatitis." (PMID 36405253, 2022). "Therefore, we further overexpressed OSGIN1 in the mouse pancreas using AAV-pan to investigate whether Osgin1 could protect against pancreatitis." (PMID 36405253, 2022). "We further identified that oxidative stress induced growth inhibitor 1 (Osgin1) was a major direct FXR target gene in pancreatic exocrine cells and mediated the protective effects of FXR activation on pancreatitis through restoration of efficient autophagy." (PMID 36405253, 2022). "Utilizing RNA-seq and ChIP-seq of PEOs, we identified Osgin1 as a direct target of FXR in the exocrine pancreas, which was also increasingly expressed in human pancreatitis tissues compared to normal pancreatic tissues." (PMID 36405253, 2022). "OSGIN1 is transcriptionally activated by direct binding of FXR to its promotor in pancreatic exocrine cells and mediates the protective effects of FXR on pancreatitis in vivo." (PMID 36405253, 2022). "Additionally, the Farnesoid X receptor (FXR)-oxidative stress-induced growth inhibitor 1 (OSGIN1) axis has been reported to promote autophagy, influencing various inflammatory-related disorders such as pancreatitis and chronic obstructive pulmonary disease." (PMID 39886963, 2025). "In this study, Osgin1 (Oxidative stress-induced growth inhibitor 1) was identified as a direct target of FXR in the exocrine pancreas, and its expression was also increased in human pancreatitis tissues compared with normal pancreatic tissues." (PMID 40243995, 2025).
osteosarcoma (2 papers, 2022 to 2024). A usually aggressive malignant bone-forming mesenchymal neoplasm, predominantly affecting adolescents and young adults. "Overexpression of a human osteosarcoma cell line (U2OS) to OSGIN1 was shown to increase ROS production and promote apoptosis via cytochrome c being released from mitochondria." (PMID 38612696, 2024). "Inhibition of PADs by their inhibitor CI-amidine leads to the upregulation of OKL38 (oxidative stress-induced growth inhibitor 1), which promotes cell apoptosis and mitochondrial dysfunction in breast and osteosarcoma cells." (PMID 34050894, 2022).
atherosclerosis (1 paper, 2022). A disease characterized by the build-up of fatty material and calcium deposition in the arterial wall resulting in partial or complete occlusion of the arterial lumen. "Our present study demonstrated that OSGIN1 is upregulated during free fatty acid-induced endothelial dysfunction, but whether OSGIN1 participated in atherosclerosis is unknown." (PMID 35625730, 2022). "We found that the atherosclerosis artery had a higher expression of OSGIN1 compared to the normal artery, especially in the endothelial layer." (PMID 35625730, 2022).
bone osteosarcoma (1 paper, 2022). A usually aggressive malignant bone-forming mesenchymal neoplasm arising from the bone. "In addition, OSGIN1 overexpression contributed to elevating cellular ROS in human bone osteosarcoma epithelial cells (U2OS cells)." (PMID 35625730, 2022).
endothelial dysfunction (1 paper, 2022). In vascular diseases, endothelial dysfunction is a systemic pathological state of the endothelium (the inner lining of blood vessels) and can be broadly defined as an imbalance between vasodilating and vasoconstricting substances produced by (or acting on) the endothelium. "We highlighted the important the XBP1s/OSGIN1 axis signaling pathway as a promising therapy to prevent endothelial dysfunction-related CVDs during vascular lipotoxicity." (PMID 35625730, 2022).
ovarian carcinoma (1 paper, 2025). A malignant neoplasm originating from the surface ovarian epithelium. "Osgin1 has been specifically linked to ovarian cancer suppression and the efficacy of chemotherapy-induced ferroptosis." (PMID 40149945, 2025).
pancreatic cancer (1 paper, 2018). "When RPL10 was knocked-down in PANC-1 and MIA PaCa-2 cells, the expression of OSGIN1 indeed markedly increased, whereas HMOX1 showed little change in both cells, indicating that RPL10 is possible to regulate ROS level in pancreatic cancer cells." (PMID 30172100, 2018).
polycystic ovary syndrome (1 paper, 2025). A disorder that manifests as multiple cysts on the ovaries. "For example, Yildrim, Tola, and Dağ (2020) have implicated underexpression of Osgin1 in polycystic ovary syndrome (PCOS), an endocrine disorder that can lead to infertility and widespread metabolic disorder." (PMID 40149945, 2025).
prediabetes (1 paper, 2022). "We found two susceptibility loci in MRPS6/SLC5A3 genes associated with 2hPG, six loci in LINC01648, MATN1, CRAT37, and SLCO3A1 genes associated with HbA1C, and five loci in TRPM3/TMEM2 and MLYCD/OSGIN1 correlated to BMI in Hainan prediabetes." (PMID 35299963, 2022).
tumor (14 papers, 2012 to 2025). "The methylation rate of CpG sites had an average increase of 54.4%, supporting the link between the downregulation of Osgin1 and increased risk for tumor growth." (PMID 40149945, 2025). "OSGIN1 gene has a strong tumor suppressor function, mainly encoding oxidative stress proteins involved in the regulation of cell death." (PMID 36985049, 2023). "This suggests that Osgin1 is involved in multiple distinct cellular pathways, with its role in tumor suppression or progression being dependent upon these pathways across cancer types." (PMID 40149945, 2025). "In turn, upregulation of SLC7A11/xCT was positively correlated with upregulation of Nrf2’s downstream targets, including Osgin1, and negatively correlated with tumor cell apoptosis." (PMID 40149945, 2025). "Building on the role of Osgin1 in tumor suppression, additional evidence is found in DNA methylation arrays of World Trade Center terrorist attack survivors." (PMID 40149945, 2025). "More interestingly, translational suppression in 5′ UTRs appeared to be key in the reduced expression of Osgin1 in the live tumor samples." (PMID 40149945, 2025). "The role of Osgin1 as a tumor suppressor in kidney carcinoma was confirmed, with transfected cells having a high rate of apoptosis." (PMID 40149945, 2025). "Furthermore, knockdown of Osgin1 and TUBB3 reversed NSCLC tumor progression, and Osgin1 knockdown additionally restored the effect of the anti-cancer drug Gefitinib in tumor suppression." (PMID 40149945, 2025). "The Adgrg1, Pdcd1, Osgin1, Lag3, and Chn2 were predominantly expressed in tumor-reactive T cells." (PMID 39243082, 2024). "Only one study has reported OSGIN1 may be a tumor suppressor that was downregulated in HCC, which contradicted our findings." (PMID 32046766, 2020). "In a comparison of 400 tumor samples from human patients to non-cancerous hepatic tissue, the full transcriptome of tissue samples was assessed to find allele imbalances, and the researchers found a specific increase in an Osgin1 variant (nt 1494: G-A, codon 438: Arg-His)." (PMID 40149945, 2025). "Therefore, our data are consistent with an emerging theme with respect to xCT-mediated tumor cell survival, and sets the stage for derivative studies aimed at determining whether targeting the xCT/OSGIN1 axis will also impact proteins involved in the PEL cell cycle." (PMID 25860939, 2015). "Enhanced OSGIN-1-mediated binding between DYRK1A and TUBB3 induces phosphorylation of TUBB3 serine 172, which effectively reduces tubulin polymerization, a mechanism of tumor migration and invasiveness." (PMID 40149945, 2025). "DNA methylation analyses of blood samples from survivors and non-survivors from 2001 showed that Osgin1 had one of the top two highest methylation differences out of 24 suspected tumor suppressor genes." (PMID 40149945, 2025). "The specific, cytoprotective regulation of OSGIN1-61 kDa under the transcriptional control of NRF2 supports an alternative mechanism for OSGIN1 independent of the recognized function of this gene in tumor cell lines." (PMID 28181536, 2017). "In contrast, the longer OSGIN1-61 kDa isoform is not shown to strongly induce apoptosis in tumor cell lines." (PMID 28181536, 2017). "Even then, this study highlights how Osgin1 may not be strictly tumor-suppressive as suggested by other papers, with tumors being able to take advantage of the protein’s autophagy pathway for cytoprotective effects." (PMID 40149945, 2025). "In conclusion, TNBC is an aggressive and heterogeneous tumor that requires more selective treatment, and the xCT/NRF2/OSGIN1 axis is a novel specific target for the treatment of MSL/CL subtypes overexpressing SLC7A11, which may be more effective than GSH depletion." (PMID 38600165, 2024).
tumor (continued). "Finally, we found that the expression of exogenous OSGIN1, similarly to the expression of exogenous NRF2, can rescue Cyss depletion-induced rapid cell death in MSL/CL TNBC cells, suggesting for the first time a role of OSGIN1 as a tumor promoter." (PMID 38600165, 2024). "The heatmap showed that 12 tumor suppressors formed into two clusters: cluster 1 contains seven downregulated tumor suppressors including PTEN, PSME1, DNAJB1, HSPH1, DEDD2, PAK1IP1, and MIR1244-3; and cluster 2 contains five upregulated tumor suppressors (OSGIN1, IFI27L1, MTCH2, NKD2, and IBTK)." (PMID 34571936, 2021).
cancer (3 papers, 2020 to 2025). A tumor composed of atypical neoplastic, often pleomorphic cells that invade other tissues. "Overall, correlational experiments illustrate that Osgin1 and Osgin2 are differentially expressed across a wide range of pathologies, including many types of cancer, infections, chronic conditions, and various other disorders." (PMID 40149945, 2025). "While the majority of research implicating the Osgin genes in disease focuses mainly on their roles in cancers, Osgin1 and Osgin2 have also been abnormally expressed in a wide variety of conditions and disorders." (PMID 40149945, 2025). "While the study does not describe a mechanistic impact, it supports an epigenetic link to carcinogenic environmental exposure to cancer development and potentially other exposure-related disease pathways via reduced expression of Osgin1." (PMID 40149945, 2025). "The current literature shows that Osgin1 and Osgin2 display differential expression in a variety of cancers and diseases, though this is, in most cases, the extent of clinical knowledge." (PMID 40149945, 2025). "In comparison with Osgin1, much less research has been performed elucidating the mechanistic role of Osgin2 in cancer." (PMID 40149945, 2025).
cardiovascular disease (1 paper, 2022). "From these literature reviews and our present study, we implicated that OSGIN1 possess the ability to fight against cardiovascular disease through preserving endothelial cell function." (PMID 35625730, 2022).
neurodegenerative disease (1 paper, 2017). A disorder of the central nervous system characterized by gradual and progressive loss of neural tissue and neurologic function.
OSGIN1 also shares sentences with these, for which no sentence is quoted: chronic obstructive pulmonary disease (1 paper); cognitive decline (1); Hydrocephalus (1); kidney cancer (1); liver cancer (1); non-small cell lung carcinoma (1); pancreatic ductal adenocarcinoma (1); prostate carcinoma (1).